ANGPTL1 (angiopoietin like 1)
Synonyms: ANG3; ANGPT3; ARP1; AngY; UNQ162; dJ595C2.2
Tractability: Antibody: UniProt places it where antibodies can reach, with high confidence; UniProt predicts a signal peptide or a membrane-spanning region; its Gene Ontology location is reachable by antibodies, with medium confidence.
Gene: Protein-coding gene on chromosome 1 (178,849,535 to 178,872,204, reverse strand). Ensembl gene ENSG00000116194.
Subcellular location: Secreted
Gene Ontology:
Molecular function: signaling receptor binding
Biological process: cell surface receptor protein tyrosine kinase signaling pathway; blood coagulation
Cellular component: extracellular exosome; extracellular region; extracellular matrix
Genetic constraint (gnomAD): Loss-of-function variants: 36 observed, 48.47 expected, observed/expected ratio (o/e) 0.74, 90% interval 0.57 to 0.98. The upper end of that interval is the gene's LOEUF score, 0.98, which puts it in group 4 of 6, group 1 being the genes least tolerant of losing a copy. Missense variants: 571 observed, 619.26 expected, observed/expected ratio (o/e) 0.92, 90% interval 0.86 to 0.99. Synonymous variants: 221 observed, 214.59 expected, observed/expected ratio (o/e) 1.03, 90% interval 0.92 to 1.15.
Homologues: Orthologues: chimpanzee ANGPTL1 (99% identical), macaque ANGPTL1 (99% identical), pig ANGPTL1 (96% identical), dog ANGPTL1 (96% identical), guinea pig ANGPTL1 (95% identical), rabbit ANGPTL1 (95% identical), mouse Angptl1 (93% identical), rat Angptl1 (93% identical), tropical clawed frog angptl1 (76% identical), zebrafish angptl1a (63% identical), zebrafish angptl1b (50% identical). Paralogues in human: ANGPTL2 (58% identical), ANGPTL6 (40% identical), ANGPT1 (27% identical), ANGPT4 (25% identical), ANGPT2 (25% identical), ANGPTL3 (25% identical), TNC (25% identical), TNR (25% identical), TNXB (25% identical), FGG (25% identical), FIBCD1 (24% identical), FGB (24% identical), and 13 more.
Diseases named in the same sentence as ANGPTL1 in open-access papers:
ANGPTL1 is named in the same sentence as 36 diseases in open-access papers, as found by Europe PMC text mining. Sharing a sentence is not in itself a finding about the gene and the disease. The quoted sentences say what the papers report.
colorectal cancer (13 papers, 2017 to 2026). A primary or metastatic malignant neoplasm that affects the colon or rectum. "For the TCGA-COAD dataset, 2 of the top genes selected by the model, SFRP4 and ANGPTL1, are known to be highly expressed in colorectal cancer (CRC) and have been linked to poor clinical outcomes in patients with CRC." (PMID 41363728, 2026). "For the TCGA-COAD dataset, two of the top genes selected by the model—SFRP4 and ANGPTL1—are known to be highly expressed in colorectal cancer (CRC) and have been linked to poor clinical outcomes in CRC patients." (PMID 40093058, 2025). "On the other hand, Angiopoietin-like protein 1 (ANGPTL1), which is known to exert metastatic suppressor activity in several cancers, is downregulated in vesicles derived from human colorectal cancers." (PMID 36831450, 2023). "Here, we integrate the possible mechanisms for ANGPTL1 inhibiting colorectal cancer liver metastasis and discuss the regulation of ANGPTL1 on the Foxo3a–Sox2 pathway." (PMID 36156125, 2022). "ANGPTL1 has been reported to suppress migration and invasion in lung, breast and colorectal cancer, acting as a novel tumor suppressor candidate." (PMID 36101384, 2022). "It has been reported that the ANGPTL1 transcript is downregulated in lung, prostate, kidney, thyroid, and urinary bladder cancer, and that ANGPTL1 suppresses metastasis in hepatocellular carcinoma, colorectal cancer, and lung cancer." (PMID 34685578, 2021). "This study was designed to explore the role of exosomal ANGPTL1 on liver metastasis in colorectal cancer (CRC)." (PMID 33413536, 2021). "For example, a few studies have demonstrated that ANGPTL1 functions as a tumor suppressor gene in breast cancer, hepatocellular carcinoma, colorectal cancer, thyroid cancer, and lung cancer." (PMID 34685578, 2021). "ANGPTL1 repressed the migration and invasion of colorectal cancer cells and was inversely correlated with poor survival." (PMID 32117620, 2020). "Recently, angiopoietin-like protein 1 (ANGPTL1), which was detected in exosomes that were derived from human colorectal cancer cells, has been shown to inhibit the liver metastasis of colorectal cancer cells by blocking MMP9-induced vascular leakiness via the JAK2-STAT3 pathway." (PMID 37047335, 2023). "Exosomal ANGPTL1 reprograms Kupffer cells and reduces their MMP9 expression, averting hepatic vascular leakage and impeding colorectal cancer liver metastases." (PMID 40475773, 2025). "In the present commentary, we discuss new observations stating that angiopoietin-like protein 1 (ANGPTL1) attenuates cancer metastasis and stemness through Forkhead box O-3a (Foxo3a)–SRY-related HMG-box-2 (Sox2) axis in colorectal cancer (Clin." (PMID 36156125, 2022).
lung carcinoma (11 papers, 2014 to 2025). "Previously, ANGPTL1 was shown to be downregulated in lung cancer patients compared to normal tissues." (PMID 39708716, 2025). "What is more, a study on lung cancer indicated that ANGPTL1 inhibited the Slug via inducing the miR-630 expression." (PMID 36156125, 2022). "Later studies proved that ANGPTL1 suppressed lung cancer metastasis by inhibiting tumor angiogenesis." (PMID 36156125, 2022). "Consistently, early studies have proved that ANGPTL1 hindered tumor metastasis in lung cancer, hepatocellular carcinoma (HCC), and CRC." (PMID 33413536, 2021). "Recently, Chen and colleagues demonstrated that ANGPTL1 inhibits sorafenib resistance and cancer stemness in HCC cells preventing MET with a mechanism similar to lung cancer, proposing, thus, ANGPTL1 as a novel MET receptor inhibitor for advanced HCC therapy." (PMID 29389861, 2018). "It has been reported that ANGPTL1 treatment significantly inhibited in vitro and in vivo migration and invasion ability of lung cancer cells." (PMID 29389861, 2018). "Of Grim-mAA-associated genes to be differentially expressed in lung adenocarcinoma and squamous cell carcinoma compared to their adjacent normal tissues, ANGPTL1, angiopoietin‐like protein 1, is a putative tumor suppressor in the lungs by repressing lung cancer cell motility." (PMID 37821974, 2023). "Additionally, ANGPTL1 represses lung cancer cell motility by abrogating the expression of the EMT mediator slug." (PMID 25370833, 2015). "Further study will be necessary to determine whether other ANGPTLs, such as ANGPTL1, ANGPTL5, ANGPTL7, also enhance metastasis in lung cancer." (PMID 26056041, 2015).
breast carcinoma (5 papers, 2014 to 2022). "An early study showed that low expression of ANGPTL1 in lung and breast cancer tissues correlated with advanced-stage, higher grade tumor and lymph node status and poorer prognosis." (PMID 28606130, 2017). "ANGPTL1 suppressed the migratory, invasive, and metastatic capabilities of lung and breast cancer cell lines in vitro and reduced metastasis in vivo (mice injected with cancer cell lines overexpressing ANGPTL1)." (PMID 24478758, 2014). "For example, ANGPTL1 overexpression in breast cancer (BC) cells could result in a significant reduction in the number and size of tumor nodules." (PMID 32410376, 2020). "Taken together, these findings suggest that ANGPTL1 may act as a novel tumor suppressor candidate in lung and breast cancer." (PMID 28606130, 2017). "It is worth noting that transcriptome profiling of metastatic canine mammary carcinomas shows the significant downregulation of ANGPT2 and ANGPTL1-4 compared to normal mammary glands." (PMID 34685578, 2021). "Angiopoietin-like protein 1 (ANGPTL1) has been reported to suppress migration and invasion in lung and breast cancer, acting as a novel tumor suppressor candidate." (PMID 28606130, 2017). "Further investigation revealed that ANGPTL1 suppressed SLUG-dependent epithelial-mesenchymal transition (EMT), thereby suppressing migratory and invasive capabilities of lung and breast cancer cell lines." (PMID 28606130, 2017).
hepatocellular carcinoma (5 papers, 2020 to 2022). A malignant tumor that arises from hepatocytes. "Inhibition of the JAK2/STAT3 pathway induced by ANGPTL1 represses angiogenesis and metastasis in hepatocellular carcinoma." (PMID 35980290, 2022). "Most of the information about the functions of the ANGPTL1 protein has come from cancer research, including its role not only in the inhibition of hepatocellular carcinoma proliferation and adhesion but also its anti-apoptotic action." (PMID 36233118, 2022). "It has also been reported that ANGPTL1 treatment remarkably inhibited in vitro and in vivo migration and invasion ability of hepatocellular carcinoma (HCC) cells." (PMID 32410376, 2020).
diabetes (2 papers, 2013 to 2021). "Taken into account into the enhancement of Angptl1 on the mesenchymal cells into osteoblasts at the early stage, Angptl1 induces trans differentiation from adipogenic-lineage into osteogenic lineage cells during bone remodeling or in the pathological state, such as diabetes and obesity." (PMID 33910546, 2021).
gastric cancer (2 papers, 2020 to 2025). A primary or metastatic malignant neoplasm involving the stomach. "Additionally, a report showed that ANGPTL3 and ANGPTL6 expression was lower in gastric cancer (GC) tissues compared to normal gastric tissues, while ANGPTL1, ANGPTL2, and ANGPTL4 were more highly expressed in GC tissues than in normal gastric tissue." (PMID 39708716, 2025). "Therefore, both ONCOMINE database and TCGA‐STAD dataset indicated that ANGPTL1/3/6 were downregulated in gastric cancer samples." (PMID 32410376, 2020). "ANGPTL1/2/4 exhibited much higher expression level than other members of ANGPTL family no matter in gastric cancer samples or in normal gastric samples (Data not shown, all P values generated by Dunn's multiple comparisons test were less than .05)." (PMID 32410376, 2020).
lung adenocarcinoma (2 papers, 2017 to 2023). A carcinoma that arises from the lung and is characterized by the presence of malignant glandular epithelial cells. "Among them, ANGPTL1 was most significantly changed, and, remarkably, it was down-regulated in 87.5% (14/16) of cancer types, including breast invasive carcinoma, lung adenocarcinoma and thyroid carcinoma." (PMID 28606130, 2017).
lymph node metastasis (2 papers, 2014 to 2022). "Ergo, there is clinical evidence that ANGPTL1 expression inversely correlates with advanced-stage lymph-node metastasis and positively correlates with survival of patients with cancer." (PMID 24478758, 2014). "In a screen of 102 patients with lung cancer, ANGPTL1 expression was found to be inversely correlated with invasion, lymph-node metastasis, and poor clinical outcomes." (PMID 24478758, 2014).
melanoma (2 papers, 2018 to 2020). A malignant, usually aggressive tumor composed of atypical, neoplastic melanocytes. "Primary melanoma tumors derived from ANGPTL1‐secreting cells grew more slowly in vivo compared to empty vector‐transfected cells." (PMID 32410376, 2020). "Effectively, ANGPTL1 overexpression in breast tumor cells resulted in a striking reduction in number and size of tumor nodules, as well as primary melanoma tumors derived from ANGPTL1-secreting cells grow more slowly in vivo compared to empty vector transfected cell." (PMID 29389861, 2018).
myeloma (2 papers, 2014 to 2023). "PCAT1, ANRIL, H19, ANGPTL1‐3, or NEAT1 upregulation induced myeloma cells insensitive to bortezomib, whereas CRNDE overexpression leads to dexamethasone tolerance." (PMID 36057947, 2023).
thyroid cancer (2 papers, 2017 to 2020). "Downregulation of ANGPTL1 was observed in kidney, lung, prostate, bladder, and thyroid cancers, too." (PMID 32410376, 2020).
atherosclerosis (1 paper, 2023). A disease characterized by the build-up of fatty material and calcium deposition in the arterial wall resulting in partial or complete occlusion of the arterial lumen. "So far, eight ANGPTLs have been discovered, from ANGPTL1 to ANGPTL8, which are involved in various biological and pathophysiological progress, including glucose and lipid metabolism, inflammation, angiogenesis and atherosclerosis." (PMID 37180779, 2023).
bone metabolic disorders (1 paper, 2021). "Our data suggest the possibility that Angptl1 might enhance and reduce osteoblastic bone formation and osteoclastic bone resorption in mice, respectively, which might leading to an increase in bone mass and a target of bone metabolic disorders, such as osteoporosis." (PMID 33910546, 2021).
colon cancer (1 paper, 2022). "Ten RNAs were finally obtained related to colon cancer, which were hsa-miR-2682-5p, hsa-miR-1277-3p, ANGPTL1, SLC22A18AS, FENDRR, PHLPP2, hsa-miR-302a-5p, APCDD1, MEX3A and hsa-miR-509-3-5p." (PMID 36101384, 2022).
colorectal tumor (1 paper, 2026). "Top genes included SFRP4 and ANGPTL1, which are both implicated in colorectal tumor aggressiveness." (PMID 41363728, 2026).
gastric tumor (1 paper, 2020). "Perhaps, ANGPTL1 played different roles in gastric tumorigenesis and gastric tumor progression." (PMID 32410376, 2020).
head and neck squamous cell carcinoma (1 paper, 2025). A squamous cell carcinoma that arises from any of the following anatomic sites: lip and oral cavity, nasal cavity, paranasal sinuses, pharynx, larynx, and salivary glands. "Selected two head and neck squamous cell carcinoma cell lines, SCC9 and CAL27, with low ANGPTL1 expression as subjects for subsequent research." (PMID 40475773, 2025).
infantile hemangioma (1 paper, 2016). "Interestingly, some of these genes also play roles in cell signaling pathways that have been linked to the pathogenesis of infantile hemangioma; namely, VEGFA in the VEGF/VEGFR pathway, ANGPT2 and ANGPTL1 in the Tie2/Angiopoietin signaling pathway and NOTCH3, NOTCH4 and JAG1 in the Notch pathway." (PMID 26772808, 2016).
invasive ductal carcinoma (1 paper, 2021). "We observed that ANGPTL1, 2, and 4 were robustly and significantly downregulated in invasive ductal carcinoma (IDC) across all microarray datasets in the GEO database." (PMID 34685578, 2021).
metabolic syndrome (1 paper, 2021). A cluster of metabolic risk factors for CARDIOVASCULAR DISEASES and TYPE 2 DIABETES MELLITUS. "Moreover, Angptl1 and Angptl2 have been reported to be involved in metabolic syndrome in human and rodents." (PMID 33910546, 2021). "These in vitro and clinical studies suggested that Angptl2 is involved in the pathophysiology of metabolic syndrome, such as obesity, although no reports are available about the roles of Angptl1 in adipobiology." (PMID 33910546, 2021).
ovarian carcinoma (1 paper, 2021). A malignant neoplasm originating from the surface ovarian epithelium. "Interestingly, ANGPTL1 has been identified in exosomes derived from saliva, urine, and ovarian cancer cells." (PMID 33413536, 2021).
pulmonary edema (1 paper, 2025). Accumulation of fluid in the lung tissues causing disturbance of the gas exchange that may lead to respiratory failure. "Another study on individuals with established high-altitude pulmonary edema (HAPE) reported that ANGPTL1 is down-regulated in response to hypoxia at high altitudes compared to individuals who are acclimatized to such conditions." (PMID 40723324, 2025).
rectal cancer (1 paper, 2022). A primary or metastatic malignant neoplasm that affects the rectum. "The mRNA expression levels of ANGPTL1/2/6 were significantly reduced in both the colon and rectal cancer tissues." (PMID 36553482, 2022).
tumor (32 papers, 2014 to 2025). "Later, the expression of ANGPTL1 in cancer tissues was explored and its association with the prognosis of patients make ANGPTL1 an attractive tumor suppressor." (PMID 36156125, 2022). "ANGPTL1 is downregulated in several malignancies, and multiple studies have evidenced its inhibitory function in tumour growth and metastasis." (PMID 40475773, 2025). "Previous studies showed that ANGPTL1 has angiogenesis-inhibiting and tumor-deactivating effects and belongs to tumor suppressors." (PMID 35692877, 2022). "Our team first found that ANGPTL1 expression was down-regulated in the exosomes derived from CRC tumor tissues." (PMID 36156125, 2022). "So far, researchers mostly focus on ANGPTL1’s impact on the primary sites, such as tumor invasiveness and mobility inhibition, which prevent tumor cells from invading nearby tissues and moving through the vascular walls." (PMID 33413536, 2021). "ANGPTL1 gene is downregulated in several tumor types (i.e., lung, prostate, kidney, thyroid, and bladder cancer)." (PMID 34445141, 2021). "In this study, we found that ANGPTL1 expression was downregulated in the exosomes derived from CRC tumor tissues than paired normal colorectal tissues." (PMID 33413536, 2021). "The anti-angiogenic effect of ANGPTL1 was also confirmed in the tumor cell lines of lung and breast cancer." (PMID 34445141, 2021). "In the case of ANGPTL1, it was shown that, with the advancement of a tumor, the concentration of the tested protein increases." (PMID 34445141, 2021). "ANGPTL1 is downregulated in various cancers, and several studies have proved its inhibitory role in tumor growth and metastasis." (PMID 33413536, 2021). "Angiopoietin-like protein 1 (ANGPTL1) has been proved to suppress tumor metastasis in several cancers." (PMID 33413536, 2021). "The results suggested that exosomal ANGPTL1 attenuated liver metastasis induced by tumor-derived exosomes in CRC." (PMID 33413536, 2021). "We studied the protein level of ANGPTL1 in exosomes derived from tumor and normal tissues in CRC patients." (PMID 33413536, 2021). "ANGPTL1 has been reported to suppress tumor metastasis in several cancers, while its extracellular effects on the PMNs are still unclear." (PMID 33413536, 2021). "ANGPTL1, a member of the angiopoietin-like protein family, inhibits tumor angiogenesis and metastasis." (PMID 34925311, 2021). "The location of tumor lesion also affected the expression level of ANGPTL1 (P = .0030), ANGPTL2 (P = .0014), ANGPTL3 (P = .0100), and ANGPTL4 (P = .0350) according to K‐W test." (PMID 32410376, 2020). "In fact, ANGPTL1 was generally supported to be a tumor suppressor across different types of tumor by both in vitro and in vivo experiments." (PMID 32410376, 2020). "As a member of angiopoietin-like protein genes, ANGPTL1 acts as a tumor-suppressor gene in various tumors." (PMID 33490103, 2020). "Down-regulation of ANGPTL1 was demonstrated in kidney, lung, prostate, bladder, and thyroid cancers when compared with non-tumor adjacent tissue." (PMID 29389861, 2018). "Apart from ANGPTL1, most ANGPTLs were also dramatically down-regulated in tumor tissues compared to the corresponding normal samples." (PMID 28606130, 2017). "Similar to our results, previous studies have reported that ANGPTL1 was significantly decreased in lung and breast tumor tissues compared to normal tissues." (PMID 28606130, 2017). "Pearson correlation analysis suggested that ANGPTL1 mRNA level was positively correlated with miR-138 level in CRC tumor samples (Pearson correlation value = 0.94, P = 0.001)." (PMID 28606130, 2017). "Analysis of 17 paired CRC and normal samples showed that ANGPTL1 was down-regulated in tumor samples (P = 0.01)." (PMID 28606130, 2017). "Notably, several ligand-receptor pairs associated with tumor progression were identified between fibroblasts and immune cells, including FN1-(ITGA8+ITGB1), FN1-CD44, COL4A2-CD44, and ANGPTL1-(ITGA8+ITGB1)." (PMID 40963856, 2025).